KBTBD3 (kelch repeat and BTB domain containing 3)
Synonyms: BKLHD3
Tractability: PROTAC: ubiquitination databases record sites on it.
Gene: Protein-coding gene on chromosome 11 (106,051,098 to 106,077,459, reverse strand). Ensembl gene ENSG00000182359.
Gene Ontology:
Molecular function: ubiquitin-like ligase-substrate adaptor activity
Biological process: proteasome-mediated ubiquitin-dependent protein catabolic process
Cellular component: Cul3-RING ubiquitin ligase complex; cytoplasm
Genetic constraint (gnomAD): Loss-of-function variants: 38 observed, 50.01 expected, observed/expected ratio (o/e) 0.76, 90% interval 0.58 to 1. The upper end of that interval is the gene's LOEUF score, 1, which puts it in group 4 of 6, group 1 being the genes least tolerant of losing a copy. Missense variants: 644 observed, 726.95 expected, observed/expected ratio (o/e) 0.89, 90% interval 0.83 to 0.95. Synonymous variants: 210 observed, 256.99 expected, observed/expected ratio (o/e) 0.82, 90% interval 0.73 to 0.92.
Homologues: Orthologues: chimpanzee KBTBD3 (100% identical), macaque KBTBD3 (99% identical), rabbit KBTBD3 (96% identical), guinea pig KBTBD3 (94% identical), pig KBTBD3 (93% identical), dog KBTBD3 (91% identical), mouse Kbtbd3 (90% identical), rat Kbtbd3 (90% identical), tropical clawed frog kbtbd3 (75% identical), zebrafish kbtbd3 (55% identical). Paralogues in human: KLHL2 (25% identical), KLHL17 (24% identical), KLHL24 (24% identical), KLHL3 (24% identical), KLHL36 (23% identical), KLHL4 (23% identical), KLHL5 (23% identical), KLHL12 (23% identical), KLHL30 (23% identical), KLHL10 (23% identical), KLHL13 (22% identical), KLHL18 (22% identical), and 42 more.